BCL2 (BCL2 apoptosis regulator)
Diseases named in the same sentence as BCL2 in open-access papers (continued):
Sharing a sentence is not in itself a finding about the gene and the disease.
neutropenia (22 papers, 2017 to 2025). A decrease in the number of neutrophils found in the blood. "The targeted inhibition of BCL‐2 for the treatment of AML has been linked to an increased risk of neutropenia, with a presumed mechanism of on‐target inhibition of BCL‐2 in neutrophil precursor cells." (PMID 40066129, 2025). "The neutrophil precursors, however, are dependent upon Bcl-2 for survival, and this dependency is proposed to underlie venetoclax’s most common adverse effect, neutropenia." (PMID 38675444, 2024). "BCL-2 inhibitors are less immunosuppressive but may cause neutropenia, increasing the risk of bacterial infections." (PMID 40647394, 2025). "Similarly, BCL-2 inhibitors have been shown to cause cytotoxic T-lymphocyte depletion and can be associated with neutropenia, further contributing to immunosuppression." (PMID 40647394, 2025). "However, the combination of ABT-263 with docetaxel exacerbated neutropenia in clinical trial, which is believed to be associated with its BCL-2 inhibitory effect." (PMID 34296214, 2020). "In addition, and has also been reported, both ABT‐263 and ABT‐199 cause neutropenia in the clinic via BCL‐2 inhibition; this neutropenia can be exacerbated by concomitant treatment with chemotherapy." (PMID 32652830, 2020). "In one trial, ≥ Grade 3 neutropenia occurred in 42% of patients treated with the BCL‐2 inhibitor venetoclax (VEN) in combination with azacitidine versus 28% of those who received azacitidine and placebo." (PMID 40066129, 2025). "Neutrophils lack several anti-apoptotic Bcl-2 proteins and depend entirely on Mcl-1 expression for survival, as shown by severe neutropenia in Mcl-1 conditional knockout (KO) mice." (PMID 41051248, 2025). "In laboratory settings, Bcl-2 inhibition with venetoclax has been shown to induce neutropenia in rats and inhibit granulocyte colony formation in human bone marrow samples." (PMID 38675444, 2024). "Intriguingly, the patients with higher BCL-2 expression experienced a longer periods of neutropenia." (PMID 37935707, 2023). "BCL-2 inhibitors alone are very well tolerated in patients with neutropenia being the most prominent on-target side effect." (PMID 36184661, 2022). "Some of the BCL2 inhibitors failed miserably in previous studies, mainly due to dose-limiting toxicity such as neutropenia and thrombocytopenia." (PMID 33976278, 2021). "This increased specificity can potentially reduce another on-target toxicity of ABT-263, i.e. neutropenia, because neutrophils depend on BCL-2 for survival." (PMID 34296214, 2020). "Even though these features open therapeutic windows for BH3 mimetics, these nevertheless have on-target toxicities, such as thrombopenia upon BCL-xL inhibition, or neutropenia upon BCL-2 inhibition." (PMID 32722518, 2020). "Despite rampant expression of BCL-2 in healthy tissues, other adverse events (AEs) were manageable, such as diarrhea, nausea and neutropenia." (PMID 32131385, 2020). "However, this activity has often come at the cost of grade III/IV neutropenia due to hematopoietic cells’ dependence on Bcl-2 for survival." (PMID 38675444, 2024). "Since BCL-2 inhibition exacerbates chemotherapy-induced neutropenia by suppressing granulopoiesis, while inhibition of BCL-XL can sensitize cancer cells to chemotherapy, DT2216 has the potential to be combined with chemotherapy for the treatment of different cancers." (PMID 34296214, 2020). "Since Bcl-2 inhibition with ABT-263 can lead to neutropenia and lymphocytopenia, the inability of DT2216 to induce Bcl-2 degradation may confer to DT2216 additional advantages by reducing the on-target toxicity of ABT263 on Bcl-2." (PMID 32677976, 2020). "Although the BCL-2 inhibitors have a number of side-effects, A1331852 and A1155463 are relatively selective BCL-XL inhibitors and appear less likely to cause neutropenia than N, making them potentially better candidates for eventual translation into clinical applications." (PMID 28273655, 2017).
neutropenia (continued). "Navitoclax, a first generation BCL-2 inhibitor targeting BCL-2 and BCL-XL, showed clinical activity, however, its use was restricted by the occurrence of neutropenia." (PMID 31555628, 2019). "Some of the BCL2 inhibitors, such as ABT737, ABT263, and ABT199, had efficient clinical relevance; however, ABT737 and ABT263 were eliminated due to dose-limiting toxicities, including neutropenia and thrombocytopenia." (PMID 33976278, 2021). "The most common Grade 3–4 non-TLS toxicity was Grade 3–4 neutropenia (~40% of patients), which is believed to be an on-target effect of BCL-2 inhibition in neutrophil progenitor cells." (PMID 30671383, 2018). "Besides the reduction of dose when using a Bcl-xL inhibitor, a key study that investigated the neutropenia induced by navitoclax, showed that this was mainly driven by the Bcl-2 inhibition, and not by the Bcl-xL one." (PMID 37720343, 2023).
type 2 diabetes (22 papers, 2014 to 2025). "Previous studies have shown that deregulation of Bcl-2 proteins in pancreatic β-cells under conditions associated with type 2 diabetes triggers apoptosis." (PMID 26064977, 2015). "Further, exogenous PAK1 induction reduced CC-3 and increased BCL2 (anti-apoptotic marker) in type 2 diabetes human islets." (PMID 39404845, 2025). "In a model of type 2 diabetes, a mix of live probiotics were able to reduce the expression of pro-apoptotic Bcl-2 and Caspase 3, while increasing levels of the anti-apoptotic protein Bax and inducing the PI3K/AKT pathway." (PMID 35757772, 2022). "The ratio of Bax to Bcl-2 represented the status of the mitochondrial apoptotic pathway which was increased in the type 2 diabetic liver." (PMID 34307690, 2021). "Under stress conditions, Bcl-2 expression levels in the hippocampi and cortices of rats with type 2 diabetes-induced neurodegeneration were significantly low (p < 0.01), while Bax expression was significantly high compared with the control group (p < 0.01)." (PMID 34834352, 2021). "On the other hand, the ratio of Bax to Bcl-2, the caspase-3 and caspase-9 mRNA levels and the number of apoptotic cells were increased in the livers of type 2 diabetic mice, which were prevented by BAIBA." (PMID 26907958, 2016). "Our study found that not only AMPK activity was significantly inhibited but also the interaction between Bcl-2 and Beclin1 was enhanced in our type 2 diabetes rats model." (PMID 27121077, 2016). "Together our results suggest that targeting the UPS and Bcl-2 protein expression may be a valuable strategy to prevent β-cell demise in type 2 diabetes." (PMID 26064977, 2015). "Additionally, YMJ pills induced apoptosis by regulating the expression of the bcl-2/bax genes at the transcriptional level in the pancreas of Otsuka Long-Evans Tokushima fatty (OLETF) rats with type 2 diabetes." (PMID 25431608, 2014). "The application of HIIT has been demonstrated to reduce the levels of apoptotic markers Bcl2-associated X protein (BAX) and BAX/B cell lymphoma/leukemia-2 (Bcl2) in BALF of mice with type 2 diabetes mellitus (T2DM)." (PMID 40182630, 2025). "The results indicated that BCL2 and LIPT1 were enriched in pathways such as neuroactive ligand receptor interaction, maturity onset diabetes of the young and RNA degradation." (PMID 39730319, 2024). "Other studies have shown that puerarin can up‐regulate B‐cell lymphoma‐2 (BCL‐2) to inhibit oxidative stress, improve liver energy metabolism dysfunction, and have a protective effect on liver oxidative damage in mice with type 2 diabetes mellitus (T2DM)." (PMID 35035928, 2022).
gallbladder cancer (21 papers, 2014 to 2025). "Moreover, the significant effects caused by overexpression of miR-138 on gallbladder carcinoma cell growth and apoptosis were reversed partially following restoration of the expression of Bag-1 with a consequential elevation of BCL-2 as well as a suppression of Bax and caspase-3 levels." (PMID 25962180, 2015). "MiR-125b upregulation would promote cell death in the presence of DDP, and Bcl2 is the target of miR-125b, mediating its function in gallbladder cancer." (PMID 38560570, 2024). "A similar pattern was demonstrated in gallbladder cancer, where low miR-125b-5p expression and high Bcl2 expression were correlated with poor prognosis." (PMID 37569592, 2023). "Autocrine TNF-α was reported to act as a tumor promoter gene by promoting gallbladder cancer cell proliferation via the AKT/NF-κB/Bcl-2 pathway." (PMID 37291206, 2023). "Subsequently, the assays suggested that melatonin significantly induced apoptosis in gallbladder cancer cells and altered the expression of the apoptotic proteins, including Bax, Bcl-2, cytochrome C, cleaved caspase-3, and PARP." (PMID 34580235, 2021). "miR-31 contributes to cisplatin resistance in gallbladder cancer via the anti-apoptotic Src/Akt/Bax/Bcl-2 signaling pathway." (PMID 34439151, 2021). "In gallbladder carcinoma, antisense-Bcl-2-siRNA against aberrantly expressed Bcl-2 gene (positive expression rate is ~23.4–51.7%) exerted significant tumor regression effect in a mouse model study." (PMID 29861465, 2018). "In summary, we showed for the first time that miR-125b-5p-Bcl2 pathway is potentially a therapeutic target for gallbladder cancer." (PMID 28256505, 2017). "We have shown that miR-125b-5p was down-regulated in gallbladder cancer samples and suppressed Bcl2 expression in vitro and in vivo." (PMID 28256505, 2017). "In clinical samples, miR-125b-5p was down-regulated in gallbladder cancer whereas Bcl2 was up-regulated and their expression was inversely correlated." (PMID 28256505, 2017). "Immunohistochemistry staining of Bcl2 showed higher Bcl2 expression in gallbladder cancer when compared with that in neighboring normal tissues." (PMID 28256505, 2017). "We identified Bcl2 as a direct target of miR-125b-5p which mediates the function of miR-125b-5p in gallbladder cancer." (PMID 28256505, 2017). "miR-125b-5p directly suppresses Bcl2 expression and increases the sensitivity of cisplatin treatment in gallbladder cancer cells and mouse models." (PMID 28256505, 2017). "Oxaliplatin demonstrated significantly greater inhibitory effects on gallbladder carcinoma cells with high MRP1, Bcl-2 or GST-π expression; in contrast, 5-fluorouracil exhibited significantly greater inhibitory effects on gallbladder carcinoma cells with low Bcl-2 or TS expression." (PMID 30016995, 2018). "The expression of Bcl2 is higher in gallbladder cancer tissues than in neighboring normal tissues." (PMID 28256505, 2017). "To investigate whether miR-125b-5p negatively regulates Bcl2 in clinical samples, we determined the Bcl2 expression in human gallbladder cancer samples." (PMID 28256505, 2017). "The expression of miR-125b-5p and Bcl2 are inversely correlated in gallbladder cancer samples." (PMID 28256505, 2017). "Immunoblotting was used to determine the expression of Bcl2 in gallbladder cancer cells." (PMID 28256505, 2017). "Moreover, low miR-125b-5p expression or high expression of Bcl2 is correlated with poor prognosis in gallbladder cancer." (PMID 28256505, 2017). "The Bcl-2 gene, which is highly expressed in gallbladder carcinoma tissues, is one of the most important regulatory factors in cell apoptosis and plays an important role in the initiation and progression of gallbladder carcinoma." (PMID 25019346, 2014).
gallbladder cancer (continued). "To investigate the molecular mechanism underlying the apoptotic effects of UA on gallbladder carcinoma cells, we assessed the expression of several apoptosis-related proteins, including PARP, caspase-3, caspase-9, cytochrome c, Bax and Bcl-2, by western blot analysis." (PMID 25383044, 2014). "Interestingly, high Bcl2 expression is correlated with poor survival in gallbladder cancer." (PMID 28256505, 2017). "Casticin isolated from Vitex rotundifolia induced apoptotsis in human gall bladder cancer cell lines SGC996 and NOZ by upregulation of Bax and down-regulation of Bcl-2 protein." (PMID 31870094, 2019). "However, whether and how Bcl2 is involved in the development of gallbladder cancer has not been studied." (PMID 28256505, 2017).
pulmonary fibrosis (21 papers, 2017 to 2025). Chronic progressive interstitial lung disorder characterized by the replacement of the lung tissue by connective tissue, leading to progressive dyspnea, respiratory failure, or right heart failure. "Treatment with ABT263 can induce apoptosis in aging pulmonary myofibroblasts and type II alveolar epithelial cells by inhibiting Bcl‐2/xl, as well as reverse changes in mouse pulmonary fibrosis caused by ionizing radiation." (PMID 37345264, 2023). "Autophagy is inhibited in fibrotic lung tissue, but miR-449a can activate autophagy via the TGF-β1/ERK/MAPK/Bcl2 axis, thereby attenuating the development of pulmonary fibrosis." (PMID 37755664, 2024). "Scutellarin can regulate the Bcl-2/Bax signaling pathway, inhibit Bcl-2 expression, promote Bax expression, induce fibroblast apoptosis, and alleviate lung fibrosis." (PMID 36825939, 2023). "Bcl-2 decreases caspase-3 activity, mediating the apoptosis resistance of macrophages, which facilitates lung fibrosis." (PMID 37569370, 2023). "Here, we found a marked increase in mitochondrial B-cell lymphoma-2 (Bcl-2) in lung macrophages from subjects with idiopathic pulmonary fibrosis (IPF)." (PMID 34413485, 2022). "Mounting evidence revealed that during pulmonary fibrosis, deregulation of Bcl-2 family proteins and imbalance between pro- and anti-apoptotic activities may determine the cellular susceptibility to apoptosis, among which Bcl-2 as an anti-apoptotic protein promotes cell survival." (PMID 34692765, 2021). "Overexpression of MiR-449a significantly activated autophagy and reduced the extent and severity of lung fibrosis induced by silica through targeting Bcl2." (PMID 29731718, 2018). "Indeed, it was reported that BAX and CAS-3 increased, and BCL-2 decreased in idiopathic pulmonary fibrosis patients." (PMID 40422811, 2025). "We found that existence of apoptosis resistance in senescent myofibroblasts in pulmonary fibrosis is dependent on “mitochondrial priming”, which may be caused by the simultaneous high expression of BAX and antiapoptotic proteins (BCL‐XL and BCL‐2)." (PMID 38831635, 2024). "The deletion of Bcl-2 in macrophages protected mice from developing pulmonary fibrosis." (PMID 34413485, 2022). "Thus, we wondered if the treatment with Bcl-2 inhibitor ABT-199 would decrease inflammation response in a model of BLM-induced pulmonary fibrosis." (PMID 34692765, 2021). "Indeed, IL-17A promotes pulmonary fibrosis by attenuating autophagy via activating the PI3-kinase/GSK3b/Bcl-2 signaling cascade in lung epithelial cells." (PMID 28039485, 2017). "By inducing Bcl-2 expression, CPT1A decreases caspase-3 activity, which attenuates macrophage apoptosis and thereby facilitates lung fibrosis progression." (PMID 37569370, 2023). "Further, we obtained in vivo evidence that early therapeutic treatment with Bcl-2 inhibitor ABT-199 from day 3, and late treatment from day 10, both alleviated airway inflammation and lung fibrosis induced by BLM." (PMID 34692765, 2021). "Higher expressions of Bcl-2 was detected in alveolar macrophages and lung fibroblasts, which displays similar expression pattern with α-SMA and the severity of lung fibrosis." (PMID 34692765, 2021). "In this study, we found that the expression of caspase-3 and Bax in the model group increased, and the expression of Bcl-2 decreased, which were all reversed by AMI treatment in a dose-dependent manner,suggesting that AMI can inhibit alveolar epithelial cell apoptosis in pulmonary fibrosis." (PMID 37380638, 2023). "Hence, in the present study, we sought to explore whether Bcl-2 is a promising target for IPF and evaluate the antifibrotic effect of ABT-199 on BLM-induced pulmonary inflammation and lung fibrosis." (PMID 34692765, 2021).
T-cell acute lymphoblastic leukemia (21 papers, 2011 to 2026). Acute lymphoblastic leukemia of T-cell origin. "However, the translation of BCL-2 could be specifically compensated by IRES activation, as researchers have reported that IRES-dependent BCL-2 contributed to the malignant element of RPL10 R98S mutation in pediatric T-cell acute lymphoblastic leukemia." (PMID 36365147, 2022). "Preclinically, it has been shown that BCL-2 is more highly expressed in early thymic precursors and decreases with T-cell maturation/differentiation, making it reasonable that precursor T-cell ALL/LBL could be highly targeted by venetoclax." (PMID 35008312, 2021). "We next wondered whether later, at 48 h after Dex treatment, there might be changes in cell morphology and anti-apoptotic Bcl-2 protein content, up-regulated in T-cell acute lymphoblastic leukemia." (PMID 25365174, 2014). "However, transplantation of MDS/MPNs co-expressing active MEK and an anti-apoptotic molecule, Bcl-2, results in T-cell acute lymphocytic leukemia (T-ALL), suggesting that longevity of cells may impact transplantability and alter disease phenotype." (PMID 22164275, 2011). "Current research has documented that in T-cell acute lymphoblastic leukemia, FBXW7 deletion results in the upregulation of MCL1, thereby conferring resistance to the BCL2 inhibitor ABT737." (PMID 40169588, 2025). "JNK V demonstrated a dose-dependent reduction in the proliferation of T-cell acute lymphoblastic leukaemia (T-ALL) cells by inducing apoptosis and cell cycle arrest, accompanied by a reduction in c-Myc and Bcl-2 protein levels." (PMID 41465323, 2025). "Moreover, cDNA microarray analysis of a human acute T cell leukemia cell line (CEM) has shown that HDIs regulate not only c-Myc, but also other genes such as Bax, Bcl-2 and Cas-3 that are involved in the intrinsic apoptotic pathway." (PMID 22684370, 2012).